IL15 (interleukin 15)
Diseases named in the same sentence as IL15 in open-access papers (continued):
Sharing a sentence is not in itself a finding about the gene and the disease.
cancer (continued). "The anti-cancer effects of IL-15 are based on the activation of CD8+ T and NK cells." (PMID 33671252, 2021). "However, more systematic analysis of IL-15 expression in solid tumours is necessary as an opposite effect of IL-15 expression in different types of cancer has been also published." (PMID 33446741, 2021). "Therefore, we determined the working doses of the BacMam-based cancer vaccine for mice by conducting a dose–response study and the cell concentration that produced the optimum level of IL-15:IL-15Rα was selected for further experiments." (PMID 34439192, 2021). "IL-15 functions by stimulating effector immune cells capable of killing cancer cells." (PMID 33671252, 2021). "Ongoing clinical trials with IL-15 engineered T cells and further preclinical work could inform the optimal mode of IL-15 delivery to enhance adoptive cell therapy for cancer." (PMID 34177932, 2021). "Emerging evidence has demonstrated that IL-15 might be a promising strategy for cancer immunotherapy." (PMID 34650926, 2021). "In coordination with immune function, IL-15 facilitates the expansion and maintenance of NK-cells and effector T-cells, while IL-6 has been shown to promote trafficking and tumor infiltration of exercise-mobilized NK-cells in several murine cancer models." (PMID 33555464, 2021). "IL-15 is one of the important biologics considered for vaccine adjuvant and treatment of cancer." (PMID 33953717, 2021). "IL-15 was discovered as a molecule highly related to interleukin-2 (IL-2), which reached the clinical setting as an approved biological drug in 1992 and was the first paradigm of successful immunotherapy of cancer." (PMID 33671252, 2021). "Additionally, IL-15 and IL-6 have known roles in activating NK-cell and T-cells during exercise and ability to facilitate the immune system and promote anti-cancer effects in preclinical models." (PMID 33555464, 2021). "Additionally, infusion of IL-15 in patients with cancer expanded CD56bright subset of NK lymphocytes and also elicited their antitumor cytotoxicity." (PMID 34359872, 2021). "Indeed, IL-15 administration potentiates the anti-cancer efficacy of cyclophosphamide, cisplatin, gemcitabine and radiation." (PMID 33671252, 2021). "Different IL-15 formulations have been tested in several cancer clinical trials." (PMID 34799399, 2021). "Several studies highlighted the potential anti-cancer efficacy of IL-15-based therapies." (PMID 33671252, 2021). "IL-15 appears to enhance the therapeutic effect of cancer-targeted NIR-PIT." (PMID 32927646, 2020). "Several IL-15 formulations are in different phases of clinical testing in cancer patients." (PMID 32461349, 2020). "Preclinical studies of IL-15 IN combination immunotherapy and cancer." (PMID 32508818, 2020). "All these features render IL‐15 a highly attractive cancer immunotherapeutic as confirmed by its high rank in the NCI's top 20 immunotherapeutic drugs with the greatest potential for broad usage in cancer therapy." (PMID 32821382, 2020). "IL-15 has recently emerged as a candidate immune-activator for the treatment of cancer." (PMID 32927646, 2020). "Clinical trials of IL-15 in combination immunotherapy of cancer." (PMID 32508818, 2020). "These new agents renew the prospect of IL-15 as a cancer immunotherapeutic agent." (PMID 32605193, 2020). "Therefore, we investigated if our IL-2/IL-15-expanded Vγ9Vδ2 T cells were also capable of improved cancer cell killing." (PMID 32983105, 2020). "Interleukin-15 enhances therapeutic effects of cancer-targeted near infrared photoimmunotherapy." (PMID 32927646, 2020). "Therefore, IL-15 can induce protective effects against cancer development with minimal effects on Tregs." (PMID 32927646, 2020). "We improved the bispecific antibody platform that primarily engages natural killer (NK) cells to kill cancer cells through antibody-dependent cellular cytotoxicity (ADCC) by adding IL-15 as a crosslinker that expands and self-sustains the effector NK cell population." (PMID 32961861, 2020).
cancer (continued). "While importance of NK and CD8+ T cells have also been indicated for IL15 based treatments, these treatments have received considerable interest for their increased Effector: Treg ratio, which is related to improved cancer therapies." (PMID 33216834, 2020). "Furthermore, our study showed the DMU-214-triggered decrease in the expression of IL1A and IL15, which are involved in enhancing cancer cell proliferation." (PMID 32046103, 2020). "In order to optimize anti-cancer activity viruses are engineered to express various immuno-stimulatory transgenes, most prominently T cell and DC activating cytokines like interleukin-2 (IL-2), interleukin-15 (IL-15) or GM-CSF91." (PMID 32542113, 2020). "Immunogenic cell death of cancer cells shortly after NIR-PIT releases damage-associated signals such as ATP, calreticulin, and high-mobility group box 1, which promotes DC maturation and subsequent effector T-cell activation mediated by IL-15." (PMID 32927646, 2020). "Moreover, a clinical study in patients reported severe GVHD in cancer patients receiving allogeneic NK cells pre-activated in vitro with IL-15 and 4-1BBL and given HLA-matched T cell-depleted allogeneic hematopoietic stem cell transplants." (PMID 33120910, 2020). "The NCI review listed IL-15 as the most promising cytokine among 12 other immunotherapeutic agents that could potentially cure cancer." (PMID 31179236, 2019). "Moreover, IL-15 has also been complexed with IL-15Rα and this novel agent has been used as an immunotherapy in cancer patients in vivo." (PMID 30842774, 2019). "These properties designate IL-15 as a candidate for cancer immunotherapy." (PMID 31623390, 2019). "These preliminary findings indicate that this IL15 superagonist complex could serve as an ideal immunostimulatory cancer therapeutic." (PMID 30654801, 2019). "The use of cytokines from the IL-2 family (also known as the common gamma chain cytokine family) such as IL-2, IL-7, IL-15 and IL-21 to activate the immune system of cancer patients is currently the one of the most important fields of cancer immunotherapy research." (PMID 31703694, 2019). "In addition, we suggest a combination of IL-15, IL-18, and IL-27 in human NK cell culture can lead to increased effectiveness of NK cell-mediated immunotherapeutics against cancers or infectious diseases." (PMID 31277710, 2019). "This study emphasizes the promise of using IL-15/IL-15Rα complex in cancer therapy and also implies that ALT-803 may improve the antitumor activity of TIL or CAR therapies in patients without increased toxic side effects." (PMID 30842774, 2019). "Survival also correlates with low serum IL-15 levels, which raises a concern regarding treating cancer patients with IL-15, which may lead to the upregulation of PD-1 and TIM-3 on T and NK cells." (PMID 30250471, 2018). "This study evaluates cancer cell-directed cytotoxicity by multi-target CTLs with and without DeepTM IL-15, which is a cell-associated crosslinked multimer of human IL15-Fc." (PMID 30400835, 2018). "IL-15 trans-presentation is being explored for cancer immunotherapy; induction of constitutive expression of IL-15 and IL-15Rα by DCs or the use of soluble IL-15/IL-15Rα complexes has been shown to enhance NK cell antitumor activity in vitro and in preclinical mouse studies (reviewed in Ref." (PMID 29491009, 2018). "However, the degree to which activating ligands expressed by cancer cells versus additional signals (e.g., from cytokines such as type I IFNs or IL-15) contribute to NK cell-dependent ignition of anti-cancer immunity remains to be elucidated." (PMID 29429633, 2018). "However, so far, few clinical trials have analyzed the security and efficacy of IL-15 in cancer patients." (PMID 28824651, 2017). "Numerous prior studies have suggested the importance of IL-15 in cancer therapy." (PMID 29255466, 2017).
cancer (continued). "Since the development of T cells, B cells, and NK cells is impaired in NSI mice, we hypothesized that a subpopulation of myeloid cells in NSI mice may respond to IL-15 stimulation and promote cancer progression." (PMID 29255466, 2017). "Thus, a Phase I study (NCT01572493) assessing the safety and efficacy of IL-15 in adults with advanced malignancies has been suspended for undisclosed reasons." (PMID 28824651, 2017). "Preclinical studies suggest that IL-15 may represent a more efficacious cytokine for cancer immunotherapy with less toxicity obtained with intermittent administration of IL-15 compared with daily administration." (PMID 28824651, 2017). "Activation of NK cells by cytokine trans-presentation has been mainly studied using IL-15;8, 33, 34, 35 IL-15 bound on an IL-15 receptor α chains (IL-15Rα of various cells such as activated monocytes, dendritic cells, and cancer cells have shown to enhance proliferation and cytotoxicity of NK cells." (PMID 28074895, 2017). "Recently, IL-15 has emerged as a potential immunotherapeutic candidate for the treatment of cancer." (PMID 28824651, 2017). "Similarities and differences between IL-2 and IL-15 effects on NK cells have been extensively reviewed elsewhere, and IL-15 might be the preferable cytokine for cancer therapy as it inhibits activation-induced cell death and it is considered safe." (PMID 28491060, 2017). "IL-15 is known to have beneficial characteristics in cancer patients." (PMID 27240402, 2016). "However, this is the first of its kind IL-15 driven TetraKE targeting two cancer markers simultaneously, one of them an established marker on cancer stem cells, CD133." (PMID 27650544, 2016). "IL-15 has been proposed as an alternative to the use of IL-2 in cancer therapy." (PMID 27356750, 2016). "IL-15 is of interest as it is closely related to IL-2 and has got the top position in the US National Cancer Institute’s ranking of 20 immunotherapeutic drugs with the greatest potential for broad usage in cancer therapy." (PMID 27686372, 2016). "Treatment of cancer patients with recombinant IL-15 may result in a reversible neutropenia but also in enhanced numbers of circulating NK cells and memory CD8+ T cells with minimal increases in Treg frequencies." (PMID 27821119, 2016). "Combining NK-cell engagers with IL-15 might represent a new generation of drugs capable of self-sustaining NK effector cells leading to a new and effective immunotherapy of cancer." (PMID 27240402, 2016). "In fact, clinical trials on IL-15 therapy for cancer treatment resulted in cytokine storm." (PMID 27684068, 2016). "An important question in the context of cancer immunotherapy is whether IL-15, as compared to IL-2, can boost γδ T cell effector functions, in terms of cytokine secretion and cytotoxic capacity." (PMID 27686372, 2016). "IL-15, has been proposed as a promising candidate to replace IL-2 for cancer therapy." (PMID 27356750, 2016). "All these functions together with animal testing demonstrating the ability of IL-15 to mediate therapeutic effects in murine transplanted tumors has generated a great deal of interest in bringing this agent to clinical testing in cancer patients." (PMID 27356750, 2016). "Thus, in this report we show that our novel IL-15/IL-15Rα designer DC are promising candidates to improve DC vaccination strategies in the battle against cancer, based on two different key points." (PMID 26675759, 2015). "IL-15 is a promising new cancer therapeutic that is well tolerated in primate models." (PMID 25879689, 2015). "Therefore, understanding the molecular mechanisms by which IL-15 primes and activates NK cells will allow the manipulation of IL-15 signaling for improving NK cell-based therapeutic strategies against cancers and infectious diseases." (PMID 26257729, 2015). "Data presented in this manuscript support a role for IL-15 in cancer immunoprevention." (PMID 25997501, 2015).
cancer (continued). "Soluble IL15 has been shown to activate NK cells, enhance NK-mediated cytotoxicity, and cytokine production in vitro, and administration of recombinant human IL15 (rhIL15) to cancer patients resulted in in vivo NK cell proliferation and activation." (PMID 26284063, 2015). "Notably, IL-15 is the most potent among them by orchestrating the entire life of NK cells and holds a great potential for immunotherapy in cancer and infectious research." (PMID 26257729, 2015). "Therefore, we sought to optimize the culture conditions for reliable expansion of γδT cells by culturing zoledronate-stimulated PBMC from both healthy individuals and patients with cancer in the presence of IL-2 plus IL-15." (PMID 25101086, 2014). "IL-15 is a central cytokine in lymphocyte development, hematopoietic malignancies, and immunotherapy, where it has paradoxically been described as both a promoter of cancer and a promoter of anti-cancer immunity." (PMID 24416335, 2014). "The role of IL-2, IL-15, IL-12, IL-18, and IL-21 in human NK cell biology is reviewed in the following sections, with emphasis on newer findings, followed by translational studies in cancer patients." (PMID 25054077, 2014). "Recent studies suggest IL-15 may stimulate effective antitumor responses in a variety of cancers, including BCa." (PMID 24896845, 2014). "Therefore, understanding the molecular mechanisms by which IL-15 primes and activates NK cells will allow manipulation of IL-15 signaling for improving NK cell-based therapeutic strategies against cancers and infectious diseases." (PMID 24795729, 2014). "The results of our study provide additional evidence of the potential efficacy of CpG and IL-15 and how it may improve vaccine approaches against cancer and infectious diseases." (PMID 23509806, 2013). "The IL-15 produced by delNS1-IL-15-infected cancer cells was biologically active." (PMID 22563505, 2012). "IL-15 is also one of several cytokines structurally similar to IL-2 that signal through the γc receptor subunit and have recently entered clinical investigation for cancer and hematologic malignancies." (PMID 24213115, 2011). "IL-2, IL-7, IL-15 and IL-21 are of particular interest in cancer immunotherapy." (PMID 21943235, 2011). "Targeting NK cells by combining DNA vaccine and immune modulators such as adjuvants (TLR agonists) and/or cytokines (e.g. IL-2, IL-15 or IL-21) could also be an exciting option as recently proposed in cancer immunotherapy." (PMID 20090916, 2010). "Both interleukin-2 (IL2) and interleukin-15 (IL15) have been used for cancer immunotherapy." (PMID 19422685, 2009). "Although IL-15 shares the same signal-transducing receptor subunits (IL-2Rβ and the common γ chain) with interleukin-2 (IL-2), the two cytokines drive fundamentally different CD8+ T-cell fates, a distinction that underlies their markedly divergent therapeutic profiles in cancer immunotherapy." (PMID 42039157, 2026). "Besides, IL‐15 may exert an antiatrophic effect, maintaining muscle mass in the presence of atrophic stimuli such as cancer cachexia, decelerating protein degradation and suppressing the ubiquitin proteolysis pathway in rats." (PMID 39764565, 2025). "IL-15 could be used as an immunostimulant in cancer therapy." (PMID 40431182, 2025). "Additionally, various studies have indicated that IL-15 signaling may play a role in promoting cancer progression." (PMID 40176196, 2025). "Additionally, since IL-15 has been reported to be effective in cancer treatment, plant-produced IL-15 may contribute to more affordable cancer therapies." (PMID 41523590, 2025). "Therefore, IL15 is considered a cytokine for treating cancer." (PMID 39396119, 2024). "This disparity underscores the potential impact of smoking on the immune system’s efficacy in cancer surveillance and response, highlighting the need for further research to elucidate the mechanisms through which smoking may influence IL-15 levels and, by extension, the immune response to HNC." (PMID 38672104, 2024).
cancer (continued). "To determine whether intracellular IL-15 also requires IL-15Rα to function, we used anti-IL-15 antibodies to immunoprecipitate cancer cell-intrinsic IL-15 and found that IL-15 was associated with IL-15Rα but not with the IL-2/IL-15Rβ or IL-2Rγ chains." (PMID 38637902, 2024). "IFN-α/β/IFN-γ/IL-15 pathways were associated with improved survival and response in patients treated with ICIs, and GBP1 could serve as a surrogate to IFN-α/β/IFN-γ/IL-15 activity in pan-cancer scale analysis." (PMID 38758367, 2024). "IL-15 can promote maturation and differentiation of immature NK cells in vivo, therefore, long-term in vitro cultures with mainly mature NK cells isolated from PBMCs of healthy donors would not faithfully recapitulate the long-term effect of XmAb24306 in cancer patients." (PMID 38515757, 2024). "Although IL2 has been approved by the US FDA, IL15 may offer more advantages in cancer treatment." (PMID 39650651, 2024). "Interestingly, we also found that ex vivo and in vivo treatments of recombinant IL-15 could induce homeostatic proliferation of Tpex cells in both a murine model of chronic viral infection and human cancer." (PMID 37409128, 2023). "Exercise-induced IL-15 might serve as a potential candidate for multiple-cancer treatments since it showed low expression in multiple cancers and predicted a better prognosis in cancer patients." (PMID 36467072, 2022). "Therefore, we hypothesized that the better prognosis of pan-cancer patients with regular exercise may be achieved by regulating level of IL-15." (PMID 36467072, 2022). "However, by our assay, we found that IL-15 variants do not seem to affect the prognosis of cancer patients (data not presented)." (PMID 36467072, 2022). "Importantly, recombinant human IL-15 has been already evaluated in cancer patients." (PMID 36230765, 2022). "Preclinical evidence suggested that exercise may modulate levels of systemic factors such as local growth factors (IGF1), hormones (insulin and leptin), and inflammatory cytokines (IL-6, IL-15), which are known factors that have a possible impact on the cancer process." (PMID 36467072, 2022). "Thus, we postulated that targeted gene delivery using transmorphic particles may potentially improve the clinical application of IL15 in cancer immunotherapy." (PMID 35758207, 2022). "This study is the first demonstration of a functionally competent soluble IL-15:IL-15Rα complex-related cancer vaccine using a baculovirus system and advocates that the BacMam system can be used as a secure and rapid method of producing a protective and therapeutic cancer vaccine." (PMID 34439192, 2021). "Challenges for IL-15 immunotherapy, however, include the inhibitory actions of immunological checkpoints that it induces, and thus there is a considerable emphasis on identifying new mechanisms of action that improve the functionality of IL-15 therapy in cancer patients." (PMID 34367174, 2021). "Thus, IL-15 has a great potential for clinical applications in the treatment of cancer." (PMID 34107983, 2021). "Therefore, the objective of our study was to define the transcriptome of canine NK cells using high throughput RNA sequencing (RNASeq) in both healthy dogs and dogs with cancer, including dogs receiving immunotherapy with inhaled IL-15 as part of a clinical trial." (PMID 34594320, 2021). "Finally, we examined whether treatment with the IL-15:IL-15Rα-B16F10-OVA vaccine could delay autologous cancer cell growth in mice." (PMID 34439192, 2021). "Also, our chimeric IL-15 might be a good adjuvant for developing the vaccine for targeting intracellular pathogens and cancers." (PMID 33953717, 2021). "However, IL-15-sushiIL-15R cancer immunotherapy showed lower antitumor efficiency than IL-15 alone." (PMID 34439192, 2021).